IL17A (interleukin 17A)
Diseases named in the same sentence as IL17A in open-access papers (continued):
Sharing a sentence is not in itself a finding about the gene and the disease.
Arthritis (continued). "Moreover, IL-17a and IL-2 plasma levels were notably elevated in IL-37atg, IL-1R8-/- mice (Figure A4A,B) compared with IL-37atg mice, indicating that IL-1R8 is essential for IL-37a-mediated suppression of arthritis and inflammatory responses." (PMID 39684587, 2024). "Thus, the role of sPLA2-IIA in arthritis implicates the mouse flora independently of IL-17A." (PMID 35076027, 2022). "The resulting arthritis could be partially blocked with monoclonal antibodies against IL-17A and IL-22 and appeared to involve an enthesis-resident IL-23 receptor expressing CD3+CD4−CD8− T cell population, which produced IL-17A and IL-22 when stimulated with IL-23 in vitro." (PMID 33983951, 2021). "In addition, Allicin could increase the Treg ratio and decrease the Th17 ratio in splenic lymphocytes of CIA model, thus inhibiting the secretion of inflammatory factor IL‐17A and further suppressing the progress of arthritis." (PMID 34026055, 2021). "However, the occurrence of skin rash, arthritis, sore throat, lymphadenopathy, hepatosplenomegaly, leukocytosis, disease activity scores, and levels of ferritin, IL-1, IL-6, IL-17A, IL-18, TNF-α, LC3-II mRNA, or ATG16L mRNA expression was not predictive of the systemic pattern." (PMID 34208077, 2021). "Therefore, we propose that reducing the enhancing effects of IL-17A in parallel with reactivating the process of cartilage regeneration may be the gold target for counteracting the pathogenesis of arthritis." (PMID 31614911, 2019). "The heterogeneous expression patterns of IL-17A, IL-17F and their receptors could perhaps explain the limited clinical response observed in clinical trials in which IL-17A in arthritis is targeted, as many patients exhibit very low IL-17 levels at the site of inflammation." (PMID 25146432, 2014). "Thus, reduction of M-CSF with the anti-IL-17A antibody treatment supports the hypothesis that bone destruction due to arthritis creates a supportive milieu for BC cells to metastasize." (PMID 24674692, 2014). "This was in contrast to arthritic mice that underwent an arthritis flare-up since a significantly lower disease score was observed in the IL-23p19 treated mice compared to the control group, accompanied by lower synovial IL-17A and IL-22 expression in the knee joints of these mice." (PMID 23469022, 2013). "Interestingly, the balance of serum IL-17A/IFNγ showed a trend to be increased (P = 0.09) at D44 if P. gingivalis oral infection was present in mice developing arthritis in the CFA/CII group compared with CFA/CII alone, and a nonsignificant trend in IL-17F/IFNγ ratios." (PMID 24456966, 2013). "Interestingly, IL-6 was required for IL-17A-induced arthritis, in Y759F mutants." (PMID 22229105, 2012). "Furthermore, IL-23 regulates IL-17A and RORγt expression in TCRγδ T cells in arthritis." (PMID 20017902, 2009). "In the AS mouse model, tacrolimus treatment resulted in significantly lower clinical arthritis scores and reduced production of inflammatory cytokines (IFN-γ, IL-17A, and TNF-α)." (PMID 40757951, 2025). "Interactions between IL-18 and STAT3 have been shown in a spontaneous arthritis model, where the activation of STAT3 mediated IL-23-induced IL-17A production from CD4+ T cells." (PMID 40777291, 2025). "The in vivo effects of tacrolimus were assessed in an AS mouse model by evaluating clinical arthritis scores and analyzing inflammatory cytokine-producing cells (IFN-γ, IL-17A, and TNF-α) via flow cytometry." (PMID 40757951, 2025). "Currently, there are emerging pharmaceuticals, including JAK inhibitors, anti-IL-6R agents, and anti-IL-17A antibodies, that show promise in the treatment of ICI-arthritis." (PMID 39122457, 2024). "As our final step, we sought to determine the functional contribution of in vitro-induced IL-17A+ CD8+ T-cells, by investigating their ability to promote clinically relevant pro-inflammatory cytokine production in an in vitro model of joint inflammation." (PMID 37367825, 2023).
Arthritis (continued). "Oral administration of nicotine reduced the IL-17A levels in CIA mice by activating α7 nAChR on the TH17 cells and led to improved clinical arthritis scores." (PMID 37893130, 2023). "Curculigoorchioides G. contains curculiglycoside, which improves arthritis symptoms in rats induced by collagen type II (CIA) and reduces levels of inflammatory factors (TNF-α, IL-1β, IL-6, IL-10, IL-12 and IL-17A)." (PMID 37893571, 2023). "Swelling of the hind paws indicative of arthritis decreased significantly compared to the vehicle treated group for the anti-TNF monotherapy (p = 0.006), anti-IL-17A monotherapy (p = 0.011) and the dual blockade therapy groups (p = 0.008)." (PMID 35055042, 2022). "NPnon-targeted treatment suppressed pro-inflammatory cytokines IL-6 by 73.3% when compared to arthritis control (p-value: 0.03); TNF-α by 42% p-value: 0.002; IL-17A by 70.6%, p-value: 0.05; and IFN-γ by 61.3%, p-value: 0.03) pg/mL." (PMID 36241847, 2022). "Results showed that kurarinone treatment reduced arthritis severity of CIA mice, as well as their levels of proinflammatory cytokines, TNF-α, IL-6, IFN-γ, and IL-17A, in the serum and paw tissues." (PMID 33924467, 2021). "Pharmacological antagonism of EP4 receptors also attenuated collagen‐induced arthritis progression with concomitant inhibition of the production of IFN‐γ and IL‐17A." (PMID 30381825, 2019). "In the ankle joint, overexpression of several proinflammatory cytokine genes started before arthritis onset, including TNFA from day 6 (p < 0.01) and IL-17A or IL-23A from day 8 (p < 0.05 and p < 0.01)." (PMID 29472591, 2018). "Data presented here demonstrate that cigarette smoking-induced aggravation of arthritis is dependent on the activation of AHR and the subsequent induction of Th17 and production of IL-17A." (PMID 29884199, 2018). "Since the immune function of CFA, the serum levels of IFN-γ, IL-6, IL-17A and TNF-α in PDCD5 tg mice and their arthritis control were significantly increased, however the production of pro-inflammatory cytokines in PDCD5 tg mice were relatively inhibited." (PMID 29228993, 2017). "Herein, we found that DXM treatment attenuated arthritis severity and proinflammatory cytokine expression levels, including TNF-α, IL-6, and IL-17A, in paw tissues of CIA mice." (PMID 28900117, 2017). "Upon examining the T cells present in the draining lymph nodes of mice with collagen-induced arthritis, we found a preferential increase in γδ T cells expressing a Vγ4Vδ4 TCR, and also showing a strong bias to secrete IL-17A." (PMID 25649119, 2015). "Several studies have demonstrated a correlation between CCR2 and Th17 cells, revealing that mice lacking CCR2 exhibit exacerbated collagen-induced arthritis due to increased Th17 cell activity and elevated levels of IL-17A, IL-6, and IL-1β." (PMID 39903705, 2025). "These experiments confirmed that SB alone mimicked key therapeutic effects of EMS, including the amelioration of arthritis, inhibition of pro-inflammatory cytokines (IL-6, TNF-α, and IL-17A), and crucially, the restoration of intestinal barrier integrity (ZO-1 and occludin)." (PMID 41309372, 2025). "Intriguingly, we found that the arthritis clinical score decreased with the administration of an IL‐17A antagonist in CAIA mice, indicating that AS‐LTEV‐enclosed IL‐17A may play a role in maintaining the inflammatory microenvironment." (PMID 39308181, 2024). "Pathogenic Th17 cells are abundantly localized in the joints of arthritic SKG mice, and IL-17A production by Th17 cells serves as the primary factor for arthritis development, as evidenced by studies in Il17a−/− SKG mice or adoptive transfer models in which Il17a−/− T cells were used." (PMID 39379604, 2024). "Based on our previous findings linking Toll-like receptor-9 (TLR9) to an EBV DNA-driven surge in IL-17A production, we aimed to examine the therapeutic potential of TLR9 inhibition in EBV DNA-exacerbated arthritis in a collagen-induced arthritis (CIA) mouse model." (PMID 38731877, 2024).
Arthritis (continued). "This is not the first finding that points to a role of the microbiota in this arthritis model, as the segmented filamentous bacteria (SFB) was found to promote the release of IL-17A in K/B×N mice: the same mice that are utilized as a source of arthritogenic serum." (PMID 35076027, 2022). "Decreased Th17 cell numbers in favor of enhanced proportions of regulatory T cells, accompanied by reduced lymphocyte IL-17A secretion and disease severity reduction, were also detected after EGCG treatment in murine models of autoimmune encephalomyelitis, arthritis, colitis, and obesity." (PMID 36012322, 2022). "Of note is that the transgenic suppression of IL-17A in sPLA2-IIATGN mice did not impact arthritis severity in this model, and intestinal permeability did not appear modulated in sPLA2-IIATGN or arthritic mice." (PMID 35076027, 2022). "This is likely a broadly conserved inflammatory axis that is not unique to trauma/hemorrhage, since IL-17A production in the context of tuberculosis, arthritis, and acetaminophen-induced liver inflammation." (PMID 35663944, 2022). "A high expression of IL17A contributes to cartilage degradation by inducing disintegrin-like and metalloproteinase with thrombospondin motifs (ADAMTS) protease and matrix metalloprotease in the articular cartilage in arthritis." (PMID 34305456, 2021). "Arthritis mice also showed higher levels of TNF-α and IL-17A in the sera." (PMID 34290703, 2021). "Altogether, the data from these SpA models indicate that IL-17A is likely not the only cytokine that contributes to the initiation of IL-23 dependent arthritis." (PMID 34267743, 2021). "Strikingly, in the B10.RII mice, the use of IL-17Amc DNA over-expression, as well as IL-17A blockade revealed no major role for IL-17A in driving arthritis in the B10.RIII model." (PMID 34267743, 2021). "Consistently, increased serum and tissue levels of IL-17 have been widely reported in inflammatory condition such as IBD, MS, and arthritis, compared to a non-pathological setting where IL-17A levels are extremely low or undetectable in human sera." (PMID 33692806, 2021). "In inflammatory conditions such as inflammatory bowel diseases and arthritis, the serum and tissue levels of IL-17 are increased relative to non-pathological settings where IL-17A levels are extremely low or undetectable." (PMID 34681582, 2021). "H&E stained sections of wrists confirmed the absence of arthritis in IL-23 EEV injected B6 mice compared to the susceptible B10.RIII strain, and there was no significant induction of Tnf, Il1b, Il17a or Il22 in the wrists of IL-23 EEV injected B6 mice." (PMID 33983951, 2021). "The high humidity (80 ± 5%) could aggravate arthritis variables including increasing arthritis score and swelling, serum autoantibodies (anti-COII and anti-CCP), and proinflammatory cytokines (IL-6, IL-17A, and G-CSF)." (PMID 34852827, 2021). "As a result, several IL-17A inhibitors are clinically available and show favorable responses in a subset of arthritis patients, but not all." (PMID 34003868, 2021). "In addition, the supernatants were collected from each group, and CBAs were used to evaluate the levels of pro-inflammatory factors (IL-17A, TNF-α and IL-6), which are closely related to arthritis progression." (PMID 29370826, 2018). "In addition, compared with arthritis control, PDCD5 tg mice reduced serum levels of the pro-inflammatory cytokines IFN-γ, IL-6, IL-17A and TNF-α and upregulated the expression of the anti-inflammatory cytokine IL-4." (PMID 29228993, 2017). "In fact, anti-IL-17A and anti-IL-17 receptor A aptamers inhibited the progression of experimental autoimmune encephalomyelitis (EAE), glucose-6-phosphate isomerase (GPI)-induced arthritis, collagen-induced arthritis, and osteoarthritis in mice." (PMID 27827561, 2017).
Arthritis (continued). "Decorin, a small molecule weight of PG, was able to induce both arthritis and fibrosis, so we used decorin that promoted MSC1 polarization to challenge murine and find if NBF of AS was a result of MSC2 polarization promoted by high level of IL-17A." (PMID 29228588, 2017). "In order to explore whether IL-17A is essential for a full expression of murine AIA, we compared the course and severity of arthritis in WT and IL-17AKO mice." (PMID 28871176, 2017). "First, it was shown that administration of anti-IL-17A mAb did not exert any effect on arthritis progression." (PMID 27313578, 2016). "The progression of arthritis in SKG mice was inhibited by the neutralization of GM-CSF and slightly by the neutralization of IL-17A, indicating that GM-CSF plays a more critical role than IL-17A in SKG arthritis." (PMID 25838639, 2015). "Digital image analysis showed a significant (P < 0.05) increase of only IL-17A in arthritis patients compared to noninflamed control tissues." (PMID 25146432, 2014). "Antigen-specific activation of naive TCR-Tg T cells lacking IFNγ in culture resulted in enhanced cytokine levels of IL-17A, which correlated with worsened uveitis but not arthritis in PG-immunized mice." (PMID 22269151, 2012). "IL-23 is comprised of the IL-23p19 subunit and the IL-12p40 subunit, (shared with IL-12), and IL-23p19-/- mice have reduced IL-17A+-Th17 cells, are resistant to collagen-induced arthritis induction, and have no joint or bone pathology." (PMID 20167120, 2010). "Low doses of IL-17a induce mechanical pain in female mice, while at higher concentrations (50 and 100 ng/mL), IL-17a increases the excitability of nociceptive receptors in the DRG neurons of male rats and enhances the sensitivity of joint nociceptors to mechanical stimuli in arthritis pain." (PMID 39859152, 2025). "However, in sPLA2-IIATGN mice, the genetic ablation of IL-17A failed to reduce the severity of arthritis." (PMID 35076027, 2022). "The levels of IL-1α and IL-17A did not change in the setting of CFA-induced arthritis." (PMID 36293292, 2022). "It has been reported that intraperitoneal injection of β-glucan increases Th17 cells 3–4-folds in the lymph nodes of SKG mice, and that T cells sorted from normal SKG mice possess the potential to cause arthritis in recipient RAG2 KO mice, but not from IL-17A KO SKG mice." (PMID 35879738, 2022). "In the CIA model mice, this study successfully demonstrated that the high humidity could aggravate RA variables including increasing arthritis scores and swelling, serum autoantibodies (anti-COII and anti-CCP), and proinflammatory cytokines (IL-6, IL-17A, and G-CSF)." (PMID 34852827, 2021). "However, IL-17A delivered using minicircles failed to induce paw inflammation, suggesting that IL-17A is incapable of initiating arthritis." (PMID 34067675, 2021). "These induced hCD8+Tregs expressed CD103 and Foxp3, did not secrete IL-17A, were stable in inflammatory conditions, had potent suppressive ability, and could alleviate collagen-induced arthritis." (PMID 30915372, 2019). "However, in the course of AIA IL-17AKO mice showed less mechanical hyperalgesia than WT mice indicating that IL-17A contributes to pain even if it is not crucial for arthritis pathology." (PMID 28871176, 2017). "It has been reported that IL-17A is strongly dependent on TNF-α in the early stages of experimental arthritis, and could induce the production of TNF-α at later stages of experimental arthritis." (PMID 24788826, 2014). "However, this study does not reveal the contribution of IL-17A-producing TCRγδ+ T cells in the arthritis process." (PMID 20017902, 2009). "Following treatment, serum levels of IL-6 and IL-17A were considerably lower at all triptolide time points, and intergroup comparisons revealed that the time of administration did not affect triptolide’s effect on arthritis score and IL-6 reduction in CIA mice." (PMID 40918529, 2025).
Arthritis (continued). "Although arthritis severity was not exacerbated by HS diet compared to RS diet in our CIA studies, IL-17A expression was analyzed in splenic CD4+-T cells of CIA mice by flow cytometric analysis." (PMID 34925335, 2021). "Collectively, these results indicate that treatment with dutasteride does not attenuate arthritis but does increase mineralization of the spine in curdlan-administered SKG mice, likely via the IL-17A pathway." (PMID 32448352, 2020). "In this model, synovial expression of IL-17A and IL-22 but not IFN-γ was lower in the anti-IL-23p19 group compared to control, highlighting the role of IL-23 in memory T cell driven flare-up arthritis." (PMID 23469022, 2013). "Consistently, levels of IL-17A, but not IFN-γ in the serum of CCR2−/− mice were significantly increased in the early phase of arthritis." (PMID 21991368, 2011). "Unlike IL-17A, TNF is considered more relevant to arthritis than skin inflammation." (PMID 41583484, 2025). "In CIA mice, alantolactone at 50 mg/kg attenuated RA symptoms, including high arthritis scores, infiltrating inflammatory cells, synovial hyperplasia, bone erosion and levels of the proinflammatory cytokines TNF-α, IL-6 and IL-17A, but not IL-10 in paw tissues." (PMID 33556301, 2021). "In this model, synovial expression of IL-17A and IL-22 but not IFN-γ was markedly lower in the anti-IL-23p19 group compared to control, highlighting the role of IL-23 in memory T cell driven flare-up arthritis." (PMID 23469022, 2013).